APOE (apolipoprotein E)
Diseases named in the same sentence as APOE in open-access papers (continued):
Sharing a sentence is not in itself a finding about the gene and the disease.
dementia (continued). "APOE ε4 carriers with the late-life physical activity in Q5 also had 66% lower risk of dementia compared with Q1 (HR, 0.34; 95% CI, 0.12-0.94)." (PMID 41259024, 2025). "It has long been known that carriers of the genotype apolipoprotein E4 (APOE-4) have a higher risk of faster progression to dementia." (PMID 41368162, 2025). "Diabetes increased the risk of incident dementia by an additional 35% in APOE ε4 carriers (relative risk: 1.35, 95% CI: 1.13–1.63)." (PMID 40641975, 2025). "Pre‐specified subgroups were defined by dementia risk factors (age, sex, education, apolipoprotein E [APOE] genotype, cognitive status, and cardiovascular risk factors)." (PMID 39821948, 2025). "While lower eBMD is associated with dementia risk, its predictive value beyond traditional factors such as age, sex, and APOE genetic risk status appears limited." (PMID 40668308, 2025). "We also found that the presence of APOE ε4 in patients with dementia and a positive family history was inversely associated with the likelihood of carrying P/LP Variants." (PMID 40427062, 2025). "This review examines the differences between ApoAI and ApoE in blood and CSF, emphasizing their distinct associations with pathological proteins, brain integrity, cognition, and dementia progression in AD." (PMID 40353050, 2025). "Any hearing loss was associated with a 71% increased risk of developing dementia, especially in persons with at least 1 apolipoprotein E ε4 allele, with hearing aid use mitigating these risks." (PMID 41191359, 2025). "This suggests that aging and APOE ε4 are associated with hypothalamic changes, highlighting mechanisms linking sleep dysfunction to dementia." (PMID 40356022, 2025). "In conclusion, we found that dream recall status was associated with blood p-tau217 levels, APOE ε4 carriage, and future cognitive decline and dementia among older adults cognitively healthy at baseline." (PMID 41001478, 2025). "But for CSF ApoAI, higher levels were associated with increased risk of dementia progression in SCD patients carrying the APOE ε4 allele." (PMID 40353050, 2025). "The top variant at this locus, rs13106836 (G/A), exhibited a pattern similar to that of APOE ε4 (rs13106836 × FOS interaction P = 0.008 for all-cause dementia; interaction P < 0.001 for vascular dementia)." (PMID 40949174, 2025). "In our study, the association between neuroticism and dementia was particularly strong among APOE ε4 carriers and former or current heavy drinkers, consistent with both factors being associated with increased dementia risk." (PMID 41275373, 2025). "The proportion of participants carrying 1 APOE ε4 allele varied widely from 24.3% of the control group to 41.2% of the incident dementia subgroup." (PMID 40568661, 2025). "The ApoE gene, particularly the ɛ4 allele, is the strongest genetic determinant of all-cause dementia." (PMID 41109864, 2025). "APOE ε4 status modified associations between midlife physical activity and incident all-cause dementia risk (P for interaction = .04)." (PMID 41259024, 2025). "One notable gene is APOE, whose risk allele APOE ε4 has been linked to vascular dysfunction, amyloid-β pathology, neurodegeneration, and ultimately, dementia." (PMID 40949174, 2025). "The effect remained significant when APOE ε4 (rs429358) allele was included in the same model, suggesting that TYROBP increases the risk of AD and dementia independently of APOE ε4." (PMID 40301889, 2025). "For example, diet fats interact with APOE to modulate cognitive decline and APOE ε4 carriers who followed a Western (less healthy) diet experienced increased dementia risk." (PMID 41008597, 2025). "We performed causal mediation analyses to decompose the total effect of APOE ε4 carriership on cognition and dementia into natural direct and indirect effects and corresponding percentage mediated." (PMID 40344552, 2025). "One study has identified significant dementia risk loci in individuals of African origin, including associations near APOE." (PMID 40289851, 2025).
dementia (continued). "Another limitation is that our observed effect sizes between chronic pain and cognitive decline (βs < .20) were modest; but this is similar to other dementia risk factors like APOE ε4." (PMID 40657909, 2025). "In terms of healthcare-related factors, lower access to and quality of healthcare were associated with increased dementia risk among APOE-ε3ε3 and APOE-ε4 carriers." (PMID 41264567, 2025). "Participants with MCI/dementia were older, less educated, with an overrepresentation of male sex, and a higher frequency of the APOE ε4 allele compared to SCD individuals." (PMID 41326959, 2025). "The connection between this pathway and major risk factors for dementia such as APOE, TREM2, c9orf72 highlights cGAS-STING pathway as a common convergence point in neuro-immune axis, affecting disease onset and progression." (PMID 41300248, 2025). "Our previous study found a dose–response relationship of possible ACD use with the risk of dementia only in APOE ε4 carriers." (PMID 41373116, 2025). "There was a significant interaction between hearing loss and APOE ε4 carrier status such that participants with at least slight hearing loss had a greater risk of dementia compared with participants with normal hearing (HR, 2.86; 95% CI, 1.12-7.28; P = .03)." (PMID 41191359, 2025). "As expected, the frequency of the APOE ε4 allele was higher in the dementia group (21.9%) compared to MCI group (19.9%) and control group (13.1%)." (PMID 41256130, 2025). "A narrative synthesis was structured according to the identified clusters across studies, their associations with dementia risk, and any moderation or stratification analyses for APOE ε4 allele carriership and C‐reactive protein (CRP), among others." (PMID 40990184, 2025). "After adjusting for age, sex, and APOE genotype, the high‐risk group had a higher risk of dementia (HR 2.24, 95% CI, 1.20–4.20, p = 0.0116) compared to the low‐risk group." (PMID 41373116, 2025). "The observation of an association of hearing loss with dementia in participants carrying the APOE ε4 allele needs replication due to the small subsample size." (PMID 41191359, 2025). "The iPRS-DEM score was associated with dementia risk (independently of APOE) in older community-dwelling people (HR: 1.15), a result which was validated in two cohorts (with improved performance in dementia-free memory clinic participants)." (PMID 40710902, 2025). "Apolipoprotein E ε4 carrier status significantly modified the association between travel modes and dementia risk, particularly for all-cause dementia and late-onset dementia." (PMID 40489111, 2025). "Studies of ApoE and its associations with pathological markers, brain integrity, cognition, and dementia progression." (PMID 40353050, 2025). "The mechanisms underlying the multiplicative interaction between the APOE ε4 genotype in dementia and CMP are multifactorial and incompletely understood." (PMID 40101131, 2025). "An ideal early biomarker for AD should capture the risks associated with both APOE ε4 allele and cardiovascular health at a preclinical, healthy stage, as well as predict conversion to dementia when risk is elevated." (PMID 41001540, 2025). "Participants with high baseline NfL concentrations had a significantly higher risk of dementia compared to those with low NfL levels (HR 1.77, 95% CI, 1.07–2.92, p = 0.0263), after adjusting for age, sex, and APOE genotype." (PMID 41373116, 2025). "This fact is backed up by some studies, which observed lower rates of accumulation of amyloid and lower dementia risk, especially among genetically vulnerable populations (e.g., APOE ε4 carriers)." (PMID 40630368, 2025). "Meanwhile, lower perceived social support and higher levels of neighborhood physical disorder were linked to greater dementia risk among APOE-ε2 and APOE-ε3ε3 carriers." (PMID 41264567, 2025).
dementia (continued). "Although social position plays a pivotal role in cognitive aging, most dementia prevention strategies and risk prediction models continue to emphasize biomedical and genetic factors (particularly APOE status)." (PMID 41264567, 2025). "In the Canadian Study of Health and Aging (CSHA), a higher prevalence of dementia, ranging from 40.6% to 57.6%, was observed in older patients who had both a stroke and the ApoE ε4 allele." (PMID 40349252, 2025). "Given evidence of a potentially protective effect of APOE2 carriage on dementia risk, 49 sensitivity analyses excluding APOE ε2/ε4 carriers (n=20) were conducted, and the results remained non-significant." (PMID 39658276, 2025). "BW was evaluated in association with dementia (Cox proportional hazards) and Aβ (logistic regression), adjusted for demographics, apolipoprotein E ε4, and vascular risk." (PMID 40891256, 2025). "Among inflammatory dermatoses, psoriasis exhibits the strongest overlap with dementia genetics, with shared susceptibility loci including APOE, IL12B, and HLA-DRB5, and transcriptional regulators such as ZNF384 that converge on IL-17/TNF signaling." (PMID 41465136, 2025). "This study elucidates the interaction between PUFAs and genetic risk factors, particularly elevated APOE genetic risk, in the incidence and mortality of dementia, highlighting significant scientific and clinical implications." (PMID 40695676, 2025). "The approximately quarter of the population who have at least one copy of the APOE e4 allele are more likely to develop dementia and also to have more age-related cognitive decline that is short of dementia than those who don’t possess it." (PMID 40386430, 2025). "These can include age or carrying an allele that increases the risk of dementia, such as the epsilon 4 allele of the Apolipoprotein E gene (APOE ε4)." (PMID 41333365, 2025). "It is important to note that mediation effects on the association between APOE ε4 and incident dementia were considerably smaller for dementia than for cognition." (PMID 40344552, 2025). "Similar associations between CNS and dementia risks were found when additionally adjusting for the status of APOE ε4 alleles." (PMID 40573071, 2025). "Compare with individuals with high dementia onset risk associated APOEε4 status, those with low-to-moderate dementia risk due to APOE genotype showed a significantly reduced risk of dementia incidence and mortality when they had higher blood levels of PUFAs." (PMID 40695676, 2025). "Apolipoprotein E (APOE) is the most common genetic risk factor for age‐related cognitive impairment (CI) and dementia." (PMID 40226865, 2025). "APOE was the first genetic locus associated with the risk of late-onset Alzheimer’s disease dementia (AD) in 1993." (PMID 40943487, 2025). "We replicated the genetic influence of APOE on dementia risk (UKB [APOE ε4 vs ε3 carriers] HR: 2.05, 1.86–2.26; AoU: 1.61, 1.44–1.80)." (PMID 41206104, 2025). "We identified 43 interaction loci modifying the associations between FOS and dementia outcomes at statistical significance stronger than that of APOE ε4." (PMID 40949174, 2025). "Higher apoE level in HDL that lacks apoC3 was associated with lower risk of dementia (hazard ratio per SD, 0.86; 95% CI, 0.76–0.99)." (PMID 40353050, 2025). "Evidence for the involvement of apoE in familial AD was observed in early studies of Down syndrome cases, in which the APP gene is triplicated, where the presence of the APOE ε2 genotype was associated with reduced risk of AD and delayed onset of dementia." (PMID 40275327, 2025). "Until now, many publications have confirmed that the best risk marker for dementia is the APOE E4 variant; however, the vast majority have relied on comparative studies of healthy individuals and those with dementia." (PMID 41226793, 2025).
dementia (continued). "This association, which was adjusted for age, sex, and apolipoprotein E genotype, indicated the role of plasma triglycerides as a common risk factor for dementia and atherosclerotic cardiovascular disease." (PMID 41470817, 2025). "A positive family history of dementia was strongly associated with APOE-e4 carriership, with individuals reporting a family history being more than twice as likely to carry an additional copy of the APOE ε4 allele compared to those without a family history." (PMID 40000321, 2025). "The APOE gene, located on chromosome 19, is the most potent genetic risk factor for Alzheimer’s disease (AD), the most common form of dementia." (PMID 39364911, 2025). "Lower hematocrit associated with increased dementia risk (adjusted hazard ratio 1.81 [1.01–3.23]) after adjusting for age, sex, race/ethnicity, education, APOE status, and comorbidities." (PMID 40026420, 2025). "Strikingly, individuals with high genetic risk (APOE-ε4) but low social adversity had a lower risk of dementia than those with low genetic risk (APOE-ε2) but high social adversity." (PMID 41264567, 2025). "ApoE genotype, a major genetic determinant of dementia, was unaccounted for, leaving inherent genetic susceptibility unadjusted." (PMID 41354966, 2025). "The authors proposed that the relative risk of conversion to dementia is lower in APOE ε4 carriers, compared to APOE ε3, because progression is likely driven by additional pathological pathways related to the ε4 allele, and unrelated to apathy." (PMID 40227643, 2025). "Twenty-five percent had at least one APOE ɛ4 allele, and 13% developed dementia during the follow up period." (PMID 40107919, 2025). "The strongest included age, sex, educational level, genotype (family history of dementia or allele producing the e4 type of apolipoprotein E [APOE e4]), parkinsonism, gait impairment and hippocampal or medial temporal volume measures." (PMID 40464216, 2025). "This study also found APOE interacts with anxiety, apathy, irritability, depression, and nighttime behaviors on incident dementia risk." (PMID 39974048, 2025). "An imbalanced N6FA/N3FA ratio increases risk, while APOE genotypes significantly modify PUFA-related dementia outcomes." (PMID 40695676, 2025). "Latent profile analysis revealed lipid-based signatures of dementia risk and resilience, shaped by genotype, sex, and APOE isoform, and supported by SIMOA protein biomarkers." (PMID 41394565, 2025). "Regarding social adversity effect by APOE alleles groups, we found that greater social adversity was related to a higher risk of dementia in all the APOE allele profiles." (PMID 41264567, 2025). "Further studies with richer covariate data—including additional risk factors for dementia and mortality, such as smoking and APOE ε4 status—are warranted to better account for residual confounding." (PMID 41123113, 2025). "Advanced age, comorbidities, lower education level, pre-existing cognitive impairment (e.g., dementia), presence of APOE allele, severity of illness." (PMID 40558594, 2025). "We developed and validated a model using AAO, EarlyFH, RelNum, parental disease status, and APOE ε4 carrier status to predict P/LP Variant carriage in patients with dementia and a positive family history." (PMID 40427062, 2025). "The apolipoprotein E (APOE) marker is a similar type of risk factor used for dementia of the Alzheimer’s type, and the measurable residual disease (MRD) testing used in oncology reflects the utility of a marker to facilitate treatment planning." (PMID 40756308, 2025). "APOE was the strongest locus associated with all-cause dementia and its two major subtypes in the time-to-event GWAS." (PMID 40949174, 2025). "Participants who were Aβ+ had greater rates of dementia and a higher prevalence of carrying the APOE ε4 allele; had lower MMSE scores; and had greater levels of plasma p‐tau217, p‐tau181, and GFAP." (PMID 39877979, 2025).
dementia (continued). "Located on chromosome 19 in the APOE gene, the allele (C) of rs429358 is one of the most extensively reported factors associated with AD risk and dementia, exhibiting an additive risk pattern." (PMID 40076709, 2025). "The impact of APOE alleles on dementia risk will be more pronounced among individuals with low social adversity as opposed to those exposed to high social adversity." (PMID 41264567, 2025). "ApoE is most prominently implicated in dementia; individuals who had been diagnosed with dementia were not included in the present study." (PMID 39967996, 2025). "Participants were classified as having low (APOE-ε2), intermediate (APOE-ε3/ε3), or high (APOE-ε4) genetic risk of dementia." (PMID 41264567, 2025). "A strong genetic risk factor for AD, the most prevalent type of dementia, is carriage of the ε4 allele of the apolipoprotein E (APOE) gene." (PMID 40221237, 2025). "Associations between APOE ε4 frequency and self-reported memory loss and dementia diagnosis were modified by descent (interaction p≤0.10)." (PMID 40791670, 2025). "At the population level, a genetic mutation of the apolipoprotein E (ApoE) gene is the strongest genetic risk factor for AD, the most common form of dementia." (PMID 40717068, 2025). "Our previous study also identified a dose–response relationship between possible ACD use and dementia risk, particularly in APOE ε4 carriers (HR 5.71, 95% CI, 2.04–15.94)." (PMID 41373116, 2025). "Although the p values for interactive effects were not stably significant regarding three different exposures and two different outcomes (all-cause dementia and AD), we still conducted subgroup analyses according to age, sex, and APOE status exploratively." (PMID 39020335, 2024). "One paediatric study investigated the effect of dementia family history in 109 children aged 11–16 years, and observed associations with worse memory and global cognition, albeit only in APOE-ε4 carriers." (PMID 39387967, 2024). "Vascular risk factors like high blood pressure, smoking, diabetes, high alcohol consumption, elevated LDL, and APOE-ε4 mutation are associated with both increased risk of stroke and dementia." (PMID 38414631, 2024). "APOE ε4 confers a stronger dementia risk in women compared to men, and is associated with earlier dementia onset in women." (PMID 38230720, 2024). "While the important role of microglia in AD is nowadays widely accepted, accumulating evidence also associates altered levels of adaptive immune cells with dementia and AD, and with APOE ε4 status." (PMID 38658964, 2024). "Another study in the Betula cohort suggested that the associations between PM2.5 and dementia were more pronounced among APOE ε4-positive participants and those with below-average odor identification ability." (PMID 38969679, 2024). "Blood pressure variability (BPV) has also emerged as a risk factor for dementia, particularly in individuals with apoE ε4." (PMID 39031528, 2024). "The APOE gene is one of the many factors linked to AD, the most prevalent type of dementia, and it is important." (PMID 38607741, 2024). "Although apathy was related to a higher progression rate to dementia among all APOE genotypes, the contribution of apathy to dementia risk was the highest among APOE e3 carriers." (PMID 38473892, 2024). "Because of her relatively young age, she did not even consider the possibility of AD (despite a strong family history of dementia) until she took a genetic test (for other reasons), which revealed her to be homozygous for the ε4 allele of ApoE (ApoE 4/4)." (PMID 39200239, 2024). "Given the substantial contribution of the APOE genotype to familial dementia risk, stratification has helped to determine additive genetic interaction and reveal associations of family history with brain health that are otherwise obscured by APOE genotype." (PMID 39387967, 2024).